KRT14 (keratin 14)
Diseases named in the same sentence as KRT14 in open-access papers (continued):
Sharing a sentence is not in itself a finding about the gene and the disease.
breast cancer (continued). "Some genes associated with cell adhesion were analyzed from this radiation- and estrogen-induced experimental breast cancer model, including E-cadherin gene CDH1, DSC3, GJA1, the Integrin alpha 6 gene ITGA6, the Integrin beta 6 gene ITGB6, the Keratin genes KRT14, KRT16, KRT17, KRT6B, and LAMB3." (PMID 36293530, 2022). "We found that TF expression in breast cancer lines and tumors closely clustered with higher levels of EMT (high vimentin/low E-cadherin) and classical basal-type biomarkers KRT5, KRT14 and caveolin-1, while it clustered with lower levels luminal-type biomarkers KRT8, KRT18, ERBB3 and ESR1." (PMID 28938620, 2017). "Finally, KRT14, a closely related KRT family of KRT13, was shown to be expressed in leader cells that participated in collective invasion of breast cancer metastasis." (PMID 27835867, 2016). "Conversely, some recent studies showed that metastatic breast cancer cells retain the expression of epithelial marker genes such as CDH1, KRT14 and JUP, which could contributed to generation of cancer cell clusters at distant organs of metastatic foci." (PMID 27258152, 2016). "Importantly, breast cancer, including TNBC, requires a basal program to promote collective migration and successful metastasis, in which there is an enrichment of cytokeratin 14 (KRT14), particularly in leader cells." (PMID 40936697, 2025). "It has long been speculated that basal-like breast cancers originate from a basal cell-of-origin as the resulting tumor lacks steroid hormone receptors and expresses specific markers restricted to the normal basal cells, such as αSMA, KRT5 or KRT14." (PMID 40676433, 2025). "Furthermore, KRT14 acquisition in the absence of cell division has also been demonstrated in breast cancer." (PMID 39408880, 2024). "Similarly, KRT5, KRT6, KRT14, and KRT17 are known to be expressed by both breast cancer and SKCM." (PMID 35267493, 2022). "Notably, the genes LDHB, MMP7, KRT5, KRT14 and KRT15, which were significantly upregulated in the PIPET_Basal subpopulation, are recognized as specific biomarkers of the basal-like molecular subtype or genes typically highly expressed in basal-like breast cancer." (PMID 38819254, 2024). "Moreover, even in nude mouse models, ADV-ApoA1 treatment markedly impeded the lung metastasis of breast cancer cells, indicating that the role of ADV-ApoA1 in inhibiting breast cancer metastasis primarily involves the regulation of the cholesterol/IKBKB/FOXO3a/KRT14 axis." (PMID 38566092, 2024).
psoriasis (62 papers, 2005 to 2025). An autoimmune condition characterized by red, well-delineated plaques with silvery scales that are usually on the extensor surfaces and scalp. "Using the IMQ-induced psoriasis model, we found that Aim2 deficiency reduces mRNA expression of the KC markers Lcn2, Krt14, and S100a9." (PMID 39352743, 2024). "Multiple enriched psoriasis-associated signaling pathways were also detected in the Krt14/Gpx4 model." (PMID 39570671, 2024). "The mRNA expression of Krt6, Krt14, and Krt16 which are associated with hyper-proliferation of keratinocytes, and of antimicrobial peptide S100a8, which is correlated with psoriasis severity, were significantly increased by imiquimod treatment in the vehicle (PBS)-injected group." (PMID 26901187, 2016). "To gain a better understanding of how epidermal SPRY1 negatively regulates the development of psoriasis, we generated K14CreERTSpry1fl/fl mice by crossing mice with loxP-flanked Spry1 alleles (Spry1fl/fl) with keratin 14-Cre/ERT (K14-CreERT) transgenic mice." (PMID 40471688, 2025). "Focusing on psoriasis as a disease model, we used high-resolution mass spectrometry imaging and identified keratin 14–expressing (K14-expressing) keratinocytes executing a ferroptotic death program in human psoriatic skin." (PMID 39570671, 2024). "Immunofluorescence staining showed that the FGF12 positive signal (red) predominantly co‐localized with the Krt14 positive signal (green) in the epidermis of both human psoriasis skin and the IMQ‐induced mouse model." (PMID 39234815, 2024). "The keratin 14 vascular endothelial growth factor (K14-VEGF) transgenic animal model can spontaneously produce psoriasis phenotype characteristics." (PMID 38203230, 2023). "In comparison with normal samples, the glycolysis score was significantly higher in psoriasis samples in KRT5+ KRT14+ KC, KRT1+KRT10+ KC, and LDHA+SLC2A1+ KC (all P<0.001)." (PMID 37205116, 2023). "Krt14‐Sprouty1 tg was used to further investigate psoriasis‐like skin inflammation, and followed by Hematoxylin and Eosin (HE) Staining, enzyme linked immunosorbent assay (ELISA), Western Blot and flow cytometry." (PMID 35716036, 2022). "Epidermis specific transgenic mouse strain (Krt14‐Sprouty1 tg) was used to further investigate psoriasis‐like skin inflammation in vivo." (PMID 35716036, 2022). "Accordingly, keratin 14-VEGF-A transgenic mice develop psoriasis, indicating its critical role in the disease." (PMID 34884834, 2021). "Transgenic mice expressing Amphiregulin under the control of keratin 14 promoter display early-onset synovial inflammation and severe skin pathology demonstrating a potential role for Amphiregulin in psoriasis and psoriatic arthritis." (PMID 16309552, 2005). "To assess whether CR influences epidermal barrier in the skin of mice with IMQ-treated psoriasis, we examined the mRNA expression levels of Krt14, Krt10, Lori, Fila and Inv by RT-PCR." (PMID 39371941, 2024). "IL-35, known as an anti-inflammatory cytokine, decreased the total number of macrophages and ratio of M1/M2 macrophages in three psoriasis models: a human keratinocyte cell line (HaCaT), a keratin 14-VEGF A-transgenic mouse model, and an imiquimod-induced psoriasis mouse model." (PMID 35837394, 2022). "To assess whether FZHFZY influences epidermal differentiation in the skin of mice with IMQ-induced psoriasis, we detected the expression of loricrin, filaggrin, involucrin, keratin 5, keratin 14 and keratin 15 in the skin by RT-PCR and western blotting." (PMID 34456715, 2021). "However, in the rERDR1-injected group, the expression of Krt6, Krt14, Krt16 and S100a8 was significantly decreased, demonstrating that rERDR1 inhibits the induction of psoriasis-like skin inflammation by imiquimod." (PMID 26901187, 2016). "By contrast, the psoriasis area and severity index (PASI: evaluates erythema and scales) and epidermal thickness were higher on the backs of Krt14+/+‐Fgf12f/f mice than the Krt14Cre/+‐Fgf12f/f mice." (PMID 39234815, 2024).
psoriasis (continued). "A depletion of cytoskeletal keratin proteins (KRT14 and KRT75) possibly alleviates the psoriasis severity." (PMID 37495626, 2023). "KRT15, KRT24, KRT31, KRT37, KRT78 are differentially expressed in psoriasis, while KRT5 and KRT14 are specific for AD." (PMID 35874668, 2022). "In our study, there is downregulated expression of loricrin, filaggrin and involucrin, but elevated expression of keratin 5, keratin 14 and keratin 15 in IL-17A/IL-22/IFN-γ/TNF-α–induced HaCaT cells and in mice with IMQ-induced psoriasis." (PMID 34456715, 2021). "The keratin 14 (K14)-vascular endothelial growth factor A (VEGF-A)-transgenic mouse model, a psoriasis animal model that overexpresses VEGF in the epidermis, can spontaneously develop a chronic inflammatory skin disease similar to human psoriasis." (PMID 35495722, 2022). "Using two-dimensional (2D) gel electrophoresis, an early study identified 21 skin proteins, including eight proteins with 2-fold increased abundance in psoriasis lesions (SERPINB4, GSTP1, SERPINB5, ARHGDIA, HSPB1, KRT14, KRT17, YWHAQ) and two others with 2-fold decreased abundance (KRT15, CALR)." (PMID 26251673, 2015). "Proteins specific to the basement membrane region (KRT14, KRT5, KRT1) were decreased only slightly in psoriasis lesions with no significant overall trend (p = 0.346)." (PMID 26251673, 2015).
epidermolysis bullosa simplex (50 papers, 2006 to 2026). Epidermolysis bullosa simplex (EBS) is a group of hereditary epidermolysis bullosa (HEB) disorders characterized by skin fragility resulting in intraepidermal blisters and erosions that occur either spontaneously or after physical trauma. "Another patient had severe Epidermolysis Bullosa Simplex with a rare c.377T > A variant resulting in substitution of amino acid p.Leu126Arg (NM_000526.5 (c.377T > G, p.Leu126Arg) in the Keratin 14 gene." (PMID 38580989, 2024). "Bolling M.C., Lemmink H.H., Jansen G.H.L., Jonkman M.F. Mutationsin KRT5 and KRT14 cause epidermolysis bullosa simplex in75 % of the patients." (PMID 36923479, 2023). "In humans and mice, frameshift-inducing Krt14 mutations cause epidermolysis bullosa simplex, a disease characterized by skin blistering that can also be caused by mutations in Plectin." (PMID 36512409, 2023). "For example, mutations in KRT5 or KRT14 are implicated in epidermolysis bullosa simplex, and KRT1 or KRT10 dysfunction causes bullous congenital ichthyosiform erythroderma; moreover, fragile skin structure is observed in almost all such conditions." (PMID 31581253, 2019). "Dominant mutations in KRT14 are responsible for the generalized severe form of epidermolysis bullosa simplex (EBS-gen sev)." (PMID 29518954, 2018). "Mutations in keratin 14 or keratin 5 cause a rare genetic disease called epidermolysis bullosa simplex." (PMID 25370987, 2015). "Dowling-Meara, the major subtype of epidermolysis bullosa simplex, is inherited in an autosomal dominant manner and can be caused by mutations in either the keratin-5 (K5) or the keratin-14 (K14) gene." (PMID 23894602, 2013). "In fact, sulforaphane, a chemical activator of Nrf2, restores skin integrity in an epidermolysis bullosa simplex model (created by Krt5 or Krt14 mutation) by activating Krt17 expression." (PMID 22567161, 2012). "Arin M.J., Grimberg G., Schumann H., de Almeida H. Jr., Chang Y.- R.,Tadini G., Kohlhase J., Krieg T., Bruckner-Tuderman L., Has C.Identification of novel and known KRT5 and KRT14 mutations in53 patients with epidermolysis bullosa simplex: correlation betweengenotype and phenotype." (PMID 36923479, 2023). "Dominantly-acting missense alleles in either KRT5 or KRT14 underlie the vast majority of cases of epidermolysis bullosa simplex (EBS), a rare genetic skin disorder in which trivial trauma results in skin blistering secondary to the lysis of fragile basal keratinocytes." (PMID 32369015, 2020). "Generalized severe epidermolysis bullosa simplex (EBS‐gen sev) is a genetic blistering skin disease in which autosomal dominant mutations in either the keratin KRT5 or KRT14 genes lead to impaired function of the intermediate filament cytoskeleton in the basal epidermis." (PMID 30099737, 2019). "Mutations in the KRT14 gene cause epidermolysis bullosa simplex (EBS), featuring abnormal basement membrane zone (BMZ) function." (PMID 39976600, 2025). "Epidermolysis bullosa simplex (EBS) is a disease arising from inherited missense mutations in KRT14 or KRT5 genes and is characterised by severe skin blistering in patients." (PMID 39408880, 2024). "In the skin fragility disorder epidermolysis bullosa simplex (EBS), mutations in keratin 14 (K14, also known as KRT14) or keratin 5 (K5, also known as KRT5) lead to keratinocyte rupture and skin blistering." (PMID 34643242, 2021). "The most comprehensibly studied one is epidermolysis bullosa simplex (EBS), a predominantly autosomal dominant disease linked to either keratin 5 or keratin 14 (K5 and K14) gene mutations." (PMID 32283594, 2020). "Generalized severe epidermolysis bullosa simplex (EBS-gen sev) is caused by mutations within either the KRT5 or KRT14 gene, phenotypically resulting in blistering and wounding of the skin and mucous membranes after minor mechanical friction." (PMID 30382914, 2018).
epidermolysis bullosa simplex (continued). "Epidermolysis bullosa simplex (EBS) is a rare genetic disorder, resulting from mutations in keratin 5 and keratin 14 (KRT14), and is characterised by skin fragility, herpetiform blistering, and the development of confluent palmoplantar keratoderma and nail dystrophy." (PMID 40700032, 2025). "For example, another dermatologic disorder, epidermolysis bullosa simplex (EBS), is associated with hotspot mutations in keratin genes KRT5 and KRT14 that result in defective cross-linking and bundle formation." (PMID 35145093, 2022). "Moreover, mutations in KRT5 and/or KRT14 are known to cause epidermolysis bullosa simplex (EBS), which is marked by skin blisters and cell fragility of basal keratinocytes." (PMID 26039063, 2015). "These mutations are located in the non-helical head (E1/V1) domain of the keratin 14 protein, as opposed to mutations in the central α-helical rod domain, which are associated with epidermolysis bullosa simplex." (PMID 40093016, 2025). "In our study, 3 patients were diagnosed with dystrophic epidermolysis bullosa (DEB) with mutations in the collagen VII alpha-1 polypeptide gene and 1 patient had an epidermolysis bullosa simplex (EBS), Dowling-Meara type, with a mutation in the keratin 14 gene." (PMID 40386013, 2025). "AD: autosomal dominant; KRT5: gene that encodes keratin 5; KRT14: gene that encodes keratin 14; EBS: epidermolysis bullosa simplex; EBS-K, epidermolysis bullosa simplex-Koebner; EBS-WC, epidermolysis bullosa simplex Weber-Cockayne; EBS-DM, epidermolysis bullosa simplex Dowling-Meara." (PMID 38803406, 2024). "Previous studies have shown that the mutation of KRT14 and KRT5 causes epidermolysis bullosa simplex; KRT14 may regulate the keratin turnover required for keratinocyte differentiation by interacting with receptor-interacting protein kinase 4 (RIPK4)." (PMID 36212119, 2022). "We began with the point mutation at the “hotspot” R125 located in the α-helical 1A domain of keratin 14 (KRT14, type I IF family), where substitution of R125 by histidine leads to the occurrence of a monogenic disease, specifically the Dowling-Meara type of epidermolysis bullosa simplex (EBS)." (PMID 34540811, 2021). "Some of the key supporting evidence comes from studies of unconventional forms of epidermolysis bullosa simplex (EBS) and other disorders resulting from KRT5 or KRT14 mutations." (PMID 34959311, 2021). "Epidermolysis bullosa simplex (EBS) is a rare skin condition usually caused by mutations in the keratin intermediate filament proteins keratin 5 (K5, also known as KRT5) or keratin 14 (K14, also known as KRT14), leading to skin blistering and wound development." (PMID 34643242, 2021). "In the case of epidermolysis bullosa simplex (EBS), which exhibits several clinical variants, specific phenotypes can be largely correlated with the positions of missense mutations in structurally sensitive portions of either KRT5 or KRT14." (PMID 26666517, 2015). "The isolated tail of human KRT14 enhances self-organization of KRT5-KRT14 filaments, and a translational frame shift near the C-terminus of KRT5, analogous to the presently observed insertion in mouse KRT90, yields a rare form of epidermolysis bullosa simplex." (PMID 36374931, 2022).
squamous cell carcinoma (29 papers, 2006 to 2025). A carcinoma arising from squamous epithelial cells. "The high molecular weight keratins (KRT5, KRT6 and KRT14) that characterize basal MIBCs are also enriched in a lethal “squamous cell carcinoma” MIBC subtype identified by another independent research group." (PMID 30550540, 2018). "In lymph node metastases of squamous cell carcinoma, tumor cells often express KRT14 in the trabecular nests of the primary carcinoma." (PMID 27556695, 2016). "In our case, however, we also found focal areas of malignant progression consistent with squamous cell carcinoma with invasion extending into follicular structures deep within the dermis as evident from cytokeratin-14 staining." (PMID 27244228, 2016). "Finally, human squamous cell carcinomas are characterized by the expression of KRT14 and KRT17." (PMID 33142242, 2020). "Squamous cell carcinoma (SQCA) of the lung and its precursor lesions express high levels of keratin 14 (K14)." (PMID 37509714, 2023). "Subsequently, we explored expression of these ARGs in pan-cancer single-cell sequencing dataset and found that only KRT14 was highly expressed in various tumors, including basal cell carcinoma (BCC), non-hodgkin lymphoma (NHL), oral squamous cell carcinoma (OSCC) and squamous cell carcinoma (SCC)." (PMID 37169018, 2023). "Mice lacking Tgfbr2 in stratified epithelia expressing Keratin 14 (K14) develop spontaneous squamous cell carcinoma (SCC) at the transition zone between the anal canal and rectum." (PMID 28219480, 2017). "Meanwhile, immunohistochemical staining of KRT14 and KRT16 in PM and MM were mostly negative, and the positive distribution contributed to the diagnosis of poorly differentiated squamous cell carcinoma." (PMID 33240619, 2020).